GBA1 (glucosylceramidase beta 1)
Diseases named in the same sentence as GBA1 in open-access papers (continued):
Sharing a sentence is not in itself a finding about the gene and the disease.
depression (continued). "In summary, our findings reveal a significantly elevated peripheral gene expression of SNCA, GBA1, and UGCG among patients currently experiencing depression which partially normalizes for GBA1 and UGCG in the group of medicated patients and also reflects increased depression severity in subgroups." (PMID 38542193, 2024). "We therefore assessed the three asymptomatic GBA1; c.115+1G>A carriers for olfactory (odor identification ability), visual and cognitive functions (Mini-Mental State Examination score), and depression (HAM-D score), which were all normal (data not shown)." (PMID 33402667, 2021). "Subset analysis showed that this clustering also occurred among biallelic GBA1 carriers alone, in terms of cognition (MoCA: OR, 2.95; 95% CI: 1.7–4.5; P = < 0.05), but not depression." (PMID 31251436, 2019).
REM sleep behavior disorder (16 papers, 2018 to 2025). A disorder characterized by episodes of vigorous and often violent motor activity during rem sleep (sleep, rem). "GBA1 p.N409S PD was associated with the highest burden of non‐motor symptoms, including REM sleep behavior disorder and cognitive/memory deficits, and LRRK2 p.G2019S with the lowest." (PMID 40926580, 2025). "Interestingly, a more recent study reported that the newly identified non-coding GBA1 rs3115534 risk variant is related to a high prevalence of REM sleep behavior disorder (RBD) symptoms in persons of Nigerian origin with PD." (PMID 39766872, 2024). "Probable REM sleep behavior disorder (RBD) had a considerably higher rate in GBA1-PD than in LRRK2-PD, whereas none of the GBA1-LRRK2-PD cases noted RBD." (PMID 39766872, 2024).
type 1 Gaucher disease (16 papers, 2013 to 2025). "Additionally, a heterozygous c.1226A>G (p.Asn409Ser) variant was found in GBA1 (NM_001005741.3), as also observed in Sample 29 and associated with Gaucher disease type 1." (PMID 40282387, 2025). "Interestingly, another study reported that 27.8% of patients with Gaucher’s disease type 1—caused by mutations in the GBA1 gene—tested positive for α-syn SAA in skin biopsies, despite only one of them having clinically established PD." (PMID 40869141, 2025). "Interestingly, one patient, P12, is a Gaucher disease Type 3C patient identified with the common variant p.Asp448His in the GBA1 gene." (PMID 38444573, 2024). "Gaucher disease type 1, a common glycolipid storage disease, is caused by deleterious mutations in GBA1, which results in dysfunction of the lysosomal enzyme, glucocerebrosidase (GCase) and subsequent excess accumulation of glucosyl-ceramide (GluCer)/-sphingosine (GluSph) in various tissues." (PMID 24124461, 2013). "The clinical heterogeneity of type 1 Gaucher disease (GD1) underscores the limited correlation between the GBA1 genotype and phenotype." (PMID 41155380, 2025). "These cytokines include IFNγ, TNFα, IL1β, IL6, IL12, IL17, IL21, and IL23 in Gba1 9V/− mouse model of type 1 Gaucher disease." (PMID 37189685, 2023). "The Gba1-prone mouse model of type 1 Gaucher disease, specifically the D409V/null; 9V/null; Gba19V/− strain, has provided valuable insights into the pathophysiology of this disorder." (PMID 37189685, 2023). "Mφs and DCs of the Gba1 9V/− mouse model of type 1 Gaucher disease have shown higher expression of C5a and C5aR1." (PMID 37189685, 2023).
Alzheimer disease (12 papers, 2013 to 2025). A progressive, neurodegenerative disease characterized by loss of function and death of nerve cells in several areas of the brain leading to loss of cognitive function such as memory and language. "Genes closely associated with Alzheimer’s disease (AD) can also influence the phenotype of GBA1 carriers." (PMID 39267121, 2024). "Moreover, the results shared in this publication support the relevance of exploring small molecule GCase modulators as a promising potential disease-modifying treatment option for aging, Alzheimer’s disease or other tauopathies beyond those directly associated with GBA1 mutations." (PMID 40399377, 2025). "Furthermore, its favorable safety profile combined with its cognitive memory-enhancing effects and its demonstrated efficacy in animal models of neurodegenerative disease, such as prion disease and Alzheimer’s disease, make it an attractive therapeutic candidate for GBA1-PD." (PMID 39388267, 2024). "Furthermore, its favorable safety profile combined with its cognitive memory-enhancing effects and its demonstrated efficacy in models of neurodegenerative disease, such as prion disease and Alzheimer’s disease, make it an attractive therapeutic candidate for GBA1-PD." (PMID 38712038, 2024).
Anxiety (10 papers, 2016 to 2025). Intense feelings of nervousness, tension, or panic often arise in response to interpersonal stresses. "Pretest counseling of the GBA1‐PD link is also unlikely to reduce screening uptake, with study participants indicating such knowledge would be beneficial and would not add any further anxiety after being given the results of a positive GBA1 variant finding." (PMID 39258449, 2024). "The α-syn PFF-injected WT and Gba1 E326K KI mice significantly reduced the time spent and the number of entries into the center zone compared to the PBS-treated mice, suggesting a change in basal anxiety levels." (PMID 37745332, 2024).
autonomic dysfunction (10 papers, 2013 to 2025). "Whether a higher burden of autonomic dysfunction, reflecting more severe impairment of the autonomic nervous system in line with the ‘body-first’ PD subtype, is a distinctive and unique trait of carriers of severe GBA1 variants, is of great interest to help understand the pathogenesis of GBA1-PD." (PMID 41034226, 2025).
Dyskinesia (10 papers, 2016 to 2025). A movement disorder which consists of effects including diminished voluntary movements and the presence of involuntary movements. "Motor complications, such as dyskinesia, dysphagia, dysarthria, freezing of gait and axial symptoms such as postural instability occur earlier and are more frequent in GBA1 MT carriers, especially in those harboring severe mutations." (PMID 36768367, 2023). "Compared to mutation-negative PD patients, GBA1-PD patients experienced a greater load of motor complications, dyskinesias, and sleep problems including RBD as well as cognitive disturbances." (PMID 39766872, 2024). "Motor complications, wearing off, delayed on and dyskinesias, are more prevalent in GBA1-PD, especially in those harbouring severe mutations, and occur earlier than in GBA1 mutation-negative PD patients." (PMID 35932311, 2022).
multiple system atrophy (8 papers, 2012 to 2025). Multiple system atrophy (MSA) is a neurodegenerative disorder characterized by autonomic failure (cardiovascular and/or urinary), parkinsonism, cerebellar impairment and corticospinal signs with a median survival of 6-9 years. "GBA1 variants have also been linked to cases of DLB and multiple system atrophy, which underlines the importance of finding biomarkers to optimize the distinction between the different α‐synucleinopathies in the early stages." (PMID 40926580, 2025).
neuroblastoma (8 papers, 2016 to 2025). Neuroblastoma (NB) is the most common solid, extracranial childhood tumor. "Two reports show decreased ceramide in CBE-treated murine cerebellar granule neurons, and in GBA1 knock-out SK-N-SH neuroblastoma cells, but overall, there is no clear trend of regional or neuronal phenotype-specific ceramide change in the GD brain." (PMID 41199336, 2025). "Indeed, exogenous GBA1 localizes to lysosomes rather than to the ER in GBA1-KO neuroblastoma cells." (PMID 38072450, 2024).
Postural instability (8 papers, 2018 to 2025). A tendency to fall or the inability to keep oneself from falling; imbalance. "The risk of progression to postural instability was increased in the GBA1-PD group in comparison with the non-carrier group." (PMID 32303560, 2020). "Moreover, GBA1 variant carriers were more likely to present with the postural instability gait difficulty phenotype compared with non-carriers and were at a more advanced Hoehn and Yahr stage after adjustment for age and disease duration compared with non-carriers." (PMID 39766872, 2024).
Fabry disease (7 papers, 2020 to 2025). Fabry disease (FD) is a progressive, inherited, multisystemic lysosomal storage disease characterized by specific neurological, cutaneous, renal, cardiovascular, cochleo-vestibular and cerebrovascular manifestations. "Another female patient with GBA1: p.R434P carried a heterozygous variant in GLA related to X-linked Fabry disease (c.937G > T chrX-101398432 C > A p.Asp313Tyr NM_000169.3)." (PMID 40542290, 2025).
Tremor (7 papers, 2016 to 2025). An unintentional, oscillating to-and-fro muscle movement about a joint axis. "In a Chinese cohort study of PD patients with 301 GBA1 and 95 L483P-PD mutations, 45 (14.86%) patients with GBA1-PD and 16 (16.84%) with L483P-PD presented tremor-dominant symptoms." (PMID 40731814, 2025). "Compared with noncarrier PD patients, tremor scores (UPDRS tremors) were significantly different, with the GBA1 group having higher scores." (PMID 40731814, 2025).
sleep disorder (6 papers, 2020 to 2025). A change from the patient's baseline sleeping pattern, in the hours slept and/or an alteration/dysfunction in the stages of sleep. "The patient’s phenotype corresponded to what is mentioned in the literature for GBA1 mutations, especially regarding the psychiatric symptoms and REM sleep disorders." (PMID 40141040, 2025). "Furthermore, motor complications such as dysphagia, also non-motor complications, such as REM (rapid eye movement) sleep disorders have also been reported more frequently in GBA1 carriers." (PMID 38153678, 2024).
Splenomegaly (6 papers, 2021 to 2025). Abnormal increased size of the spleen. "Patient 6: A 60-year-old woman presented at age 21 with massive splenomegaly and thrombocytopenia and was found to be compound heterozygous for the GBA1 mutations p.Asn409Ser and p.Val433Leu." (PMID 41282474, 2025). "Patient 7: An adult man, who initially presented at age 14 with splenomegaly and thrombocytopenia, was diagnosed with GD1 due to homozygosity for the p.Asn409Ser GBA1 mutation and commenced ERT." (PMID 41282474, 2025). "The proband was an Ashkenazi Jewish male diagnosed with type 1 GD (GBA1: N370S/N370S) at age 61, when he presented with thrombocytopenia, osteopenia, and mild splenomegaly." (PMID 40667145, 2025). "This is earlier than the splenomegaly development in the type 3 GD 4L/PS-NA model, GD mouse model, and the GBA1 model, which was 3 months, 12 months and 14 months, respectively." (PMID 40430940, 2025). "Patient 1: A 42-year-old man presented with mild splenomegaly, thrombocytopenia, and osteopenia and was diagnosed with GD1 due to homozygosity for the p.Asn409Ser GBA1 mutation." (PMID 41282474, 2025). "The clinical features of human GD that happens due to GBA1 defect includes anemia, thrombocytopenia, hypergammaglobulinemia, splenomegaly, hepatomegaly, bone and brain defects)." (PMID 34884512, 2021).
liver cancer (5 papers, 2022 to 2025). An epithelial or non-epithelial malignant neoplasm that arises from the liver. "In chronic lymphocytic leukemia (CLL), C16:0 GlcCer specifically supports leukemic cell survival and proliferation, whereas C18:0 GlcCer has been implicated in GBA1-dependent liver cancer metastasis." (PMID 41155172, 2025). "In conclusion, we demonstrated that GBA1 is downregulated in liver cancer, and the low expression of GBA1 is associated with vascular invasion and an advanced stage of liver cancer." (PMID 35637196, 2022). "The results of this study indicate that a GBA1-dependent increase in GlcCer can act as a hallmark of liver cancer metastasis." (PMID 35637196, 2022). "To further study the functional role of GBA1 in liver cancer, we performed gain- and loss-of-function studies in vitro." (PMID 35637196, 2022). "The ROC curve for liver cancer diagnosis was 86% in this study, indicating that GBA1 is a potential diagnostic biomarker for liver cancer." (PMID 35637196, 2022). "To confirm that GBA1 suppresses the metastasis of liver cancer, we examined the effect of GBA1 deficiency on the growth and metastasis of liver cancer using an orthotopic xenograft model." (PMID 35637196, 2022). "A clinical relevance analysis revealed that low expression of GBA1 was associated with the metastatic potential of liver cancer cells." (PMID 35637196, 2022). "Taken together, this gain- and loss-of-function study in vivo confirmed that GBA1 inhibition promotes metastasis of liver cancer." (PMID 35637196, 2022). "Similarly, C18:0 GlcCer has been implicated as a driver of GBA1-dependent liver cancer metastasis." (PMID 41155172, 2025). "GBA1-dependent GlcCer metabolism reprogramming in the plasma membrane promotes liver cancer metastasis by activating Wnt/β-catenin signalling." (PMID 35637196, 2022). "Mechanistic studies indicated that low expression of GBA1 enhanced the metastatic ability of liver cancer by promoting the epithelial-mesenchymal transition (EMT), in which Wnt signalling pathway is involved." (PMID 35637196, 2022). "Because GlcCer was increased in liver cancer and GBA1 is an important catabolic enzyme of GlcCer, next we focused on GBA1." (PMID 35637196, 2022). "In this study, we demonstrated that the protein expression of GBA1, which catalyses the conversion of GlcCer to ceramide, was downregulated in liver cancer tissue." (PMID 35637196, 2022). "Although a change in LRP6 level/location in the plasma membrane after regulation of GBA1 in liver cancer was observed in this study, the mechanism, such as inhibition of receptor internalisation, needs to be studied in greater depth." (PMID 35637196, 2022). "As GlcCer has been proved to have a relationship with chemotherapy resistance in cancers, we also investigated the relationship between GBA1-dependent GlcCer reprogramming in the liver cancer cell and sorafenib resistance." (PMID 35637196, 2022). "We also demonstrated that the GBA1 protein is downregulated in liver cancer, especially in patients with vascular invasion." (PMID 35637196, 2022). "Herein, we demonstrate that GBA1-mediated GlcCer metabolism reprogramming in the plasma membrane promotes liver cancer metastasis via activation of the Wnt/β-catenin signalling pathway." (PMID 35637196, 2022). "Besides, we also found downregulation of GBA1 inhibited sorafenib sensitivity of liver cancer cells." (PMID 35637196, 2022). "Although mutation of GBA1 increases the incidence of cancer, including liver cancer, and one recent study showed that inhibition of GBA1 leads to reversal of gastric cancer chemoresistance, the role of GBA1 in cancer progression remains largely unknown." (PMID 35637196, 2022). "Given that GBA1 is an enzyme in glucosylceramide catabolism, we hypothesised that low expression of GBA1 in liver cancer promotes the EMT via activation of the Wnt signalling pathway." (PMID 35637196, 2022).
liver cancer (continued). "In addition to PDMP, miglustat which is another inhibitor of GCS has a similar effect on Wnt activation and metastasis, These results demonstrated that GBA1 inhibition promotes metastasis of liver cancer in which GlcCer is involved." (PMID 35637196, 2022). "All these data indicated that downregulation of GBA1 in liver cancer cell may favour the resistance to chemotherapy, and it is of great significance in the chemotherapy strategy for liver cancer." (PMID 35637196, 2022). "Furthermore, loss- and gain-of-function studies confirmed that low expression of GBA1 promoted metastasis of liver cancer both in vitro and in vivo." (PMID 35637196, 2022). "Furthermore, as GBA1 is expressed at low levels in liver cancer, upregulation of GBA1 may be a potential therapeutic strategy to combat the metastasis of liver cancer." (PMID 35637196, 2022). "Upregulation of GBA1 may be a novel therapeutic strategy for combating liver cancer metastasis." (PMID 35637196, 2022). "Silence of GBA1 could increase the cell vitality by 4.3-fold in Huh7s under sorafenib exposure, and overexpression of GBA1 revealed opposite effect, indicating that low expression of GBA1 could increase chemotherapy resistance of liver cancer cells against sorafenib." (PMID 35637196, 2022). "In addition, the results of mass spectrometry indicated that GlcCer d18:1/18:0 was the most notably increased studied species in the PM when GBA1 was downregulated, suggesting that GlcCer d18:1/18:0 may be the major functional lipid that promotes GBA1-dependent liver cancer metastasis." (PMID 35637196, 2022). "In this study, we found that the catabolic enzyme GBA1 regulates GlcCer metabolism in the plasma membrane, down regulation of GBA 1 promoting metastasis of liver cancer both in vitro and in vivo." (PMID 35637196, 2022). "Thus, GBA1-mediated GlcCer reprogramming in the PM promotes metastasis of liver cancer via activation of the Wnt/β-catenin signalling pathway, upregulation of GBA1 may be a potential therapeutic strategy to combat liver cancer metastasis." (PMID 35637196, 2022). "Furthermore, when GBA1 was downregulated, GlcCer d18:1/18:0 was the most notably changed tested species in the plasma membrane, suggesting that GlcCer d18:1/18:0 may be the major functional lipid that promotes GBA1-dependent liver cancer metastasis." (PMID 35637196, 2022). "We found that the protein level of GBA1 decreased significantly in liver cancer tissues compared to paired adjacent nontumorous liver tissue." (PMID 35637196, 2022). "The results showed that GBA1 was downregulated in liver cancer tissues compared to paired adjacent nontumorous liver tissues." (PMID 35637196, 2022). "First, the expression of GBA1 at the protein level in liver cancer tissue and paired adjacent nontumorous liver tissue was determined by immunohistochemistry (IHC)." (PMID 35637196, 2022). "Furthermore, no metastatic lesions in the lung were observed in the mice with liver cancer that had been established by MHCC-97H cells overexpressing GBA1, indicating that GBA1 overexpression suppressed the metastasis of liver cancer to the lung." (PMID 35637196, 2022). "Then, the mRNA expression of GBA1 in liver cancer tissues and adjacent nontumorous liver tissues was determined by real-time PCR, and we found that the ratio of low GBA1 expression was higher in patients with portal vein tumour thrombus (PVTT) than in those without PVTT." (PMID 35637196, 2022). "Furthermore, the expression of GBA1 in liver cancer with vascular invasion was reduced compared to that without vascular invasion." (PMID 35637196, 2022). "However, the proportion of normal liver tissue was greater in the mice in which liver cancer had been established with MHCC-97H cells overexpressing GBA1, indicating that overexpression of GBA1 may help preserve normal liver tissue and prevent liver cancer invasion." (PMID 35637196, 2022).
psychosis (5 papers, 2022 to 2025). "Interestingly, despite carrying risk variants in both LRRK2 and GBA1, dual mutation carriers (LRRK2-GBA1-PD) tend to exhibit a lower frequency of RBD and psychosis than patients with single GBA1 mutations, suggesting a complex and possibly modulating interaction between these genetic factors." (PMID 40422213, 2025). "Psychosis and other psychiatric symptoms may also be more frequent in GBA1 carriers." (PMID 39766872, 2024). "For example, patients with GBA1-associated PD have shown a higher prevalence of non-motor features, such as dementia, probable REM sleep behavior disorder (RBD), and psychosis, in contrast to those with LRRK2-PD or MNPD." (PMID 40422213, 2025). "Psychosis was most common in GBA1-PD and least common in LRRK2-GBA1-PD." (PMID 39766872, 2024).